VEGFA (vascular endothelial growth factor A)
Diseases named in the same sentence as VEGFA in open-access papers (continued):
Sharing a sentence is not in itself a finding about the gene and the disease.
tumor (continued). "DYRK1A was found to be coexpressed with several STAT3 target genes, including zinc finger E-box-binding homeobox 1, VEGFA and heat shock protein 90, in clinical tumour samples from patients with HCC." (PMID 35655269, 2022). "NDRG1, BHLHE40 and VEGFA, which were found in tumour cluster B, mainly affect tumour proliferation, metastasis and invasion." (PMID 35109839, 2022). "Vascular endothelial growth factor A (VEGFA) secreted by hypoxic cancer cells initiates tumor angiogenesis by interacting with VEGF receptor 2 (VEGFR2) expressed by adjacent vascular ECs." (PMID 36185269, 2022). "The downregulation of VEGFA secretion from CAFs helps block angiogenesis and exerts an anti-tumor effect." (PMID 35626012, 2022). "The AUC values for 1-, 3-, and 5 years were 0.785, 0.837, and 0.765, respectively, indicating the robustness and accuracy of the VEGFA gene in predicting patient tumor progression and prognosis." (PMID 35785190, 2022). "Emerging studies have indicated that VEGFA overexpression tends to involve a suppressive tumor microenvironment (TME) and decreased antitumor immunity, further mediating primary resistance to the anti-PD-(L) 1 regimen." (PMID 35488336, 2022). "For example, known HCC-related genes (NDRG1 and VEGFA) are among the most highly expressed genes in the “tumour” clusters." (PMID 35109839, 2022). "This study found that LFE can downregulate the expression of VEGFA protein, thus inhibiting the angiogenesis of liver tumors and hindering the migration and invasion of tumor cells." (PMID 36110518, 2022). "Studies on animal models of cancer progression have reported that tumor cells secrete lymphangiogenic factors, including VEGFA, VEGFC, and VEGFD; induce active metastasis; and promote the circulation of cancer cells into LNs and other sites." (PMID 35626729, 2022). "Tumour cells-derived VEGFA, which contribute to promote tumour growth and metastasis, is involved in the inhibition of DCs maturation." (PMID 35406451, 2022). "Semaphorin 3A is also increased (together with VEGFA) in hypoxic conditions in mouse Lewis lung carcinomas and this will promote the retention of pro-tumoral macrophages in the hypoxic tumor microenvironment." (PMID 35216427, 2022). "While anti-VEGFA agents have been extensively studied in endothelial and tumor cells, their effects on osteoblasts of the jaw bone that are most likely involved in the development of MRONJ remain elusive." (PMID 35171372, 2022). "VEGFA overexpression contributes to unlimited tumor growth and vascularization in BC, especially TNBC." (PMID 35711946, 2022). "As previously observed in vitro, pladienolide B administration in vivo significantly decreased various relevant tumor progression markers and critical oncogenic spliceosome components (VEGFA/EGFR/CDK4/PDGFRA/PDGFRB and SRSF3/PTBP1)." (PMID 35086552, 2022). "Tumor cells release several pro-angiogenic factors, such as vascular endothelial growth factor A (VEGFA), which promote neovascularization in the tumor immune microenvironment (TIME)." (PMID 35572524, 2022). "VEGFA around endothelial cells in the tumor microenvironment is partly derived from autocrine and mostly from paracrine of tumor cells." (PMID 36467048, 2022). "In detail, lung nodules were tremendously decreased and tumor cell proliferation and metastasis that are marked with Ki‐67 and VEGFA, respectively, were blockaded." (PMID 36156442, 2022). "The suppression of miR-146a-5p simultaneously inhibited angiogenesis and the expression of the proangiogenic protein EMMPRIN in tumor cells.This study showed that both overexpressed miR-146a-5p and exosomal miR-146a-5p increased VEGFA expression." (PMID 35548775, 2022). "Vascular endothelial growth factor A serves as an essential angiogenic cytokine in tumor angiogenesis; it is therefore that it can be a potential for the research of cancer therapy." (PMID 35945960, 2022).
tumor (continued). "Among them, c-FLIP participates in tumour progression correlates with poor prognosis; and VEGFA contributes to cell growth and malignant transformation." (PMID 35106125, 2022). "We next examined the expression of RTK ligands, including HGF, EFNA5, and VEGFA, in the membranes of tumor cells." (PMID 35205843, 2022). "In this paper, the tumor tissue sections after 2′-FL treatment were analyzed, and the effect of 2′-FL on VEGFA/VEGFR2/PI3K/Akt was investigated." (PMID 36364081, 2022). "The activation of STAT3 helps tumor cells to evade NK cell-mediated immune surveillance, which is associated with high expression of tumor-promoting cytokines and growth factors, such as IL-10, TGF-β, and vascular endothelial growth factor-A." (PMID 36601109, 2022). "Collectively, these data strongly implied that GSK3α regulated tumor angiogenesis via the HIF1α/VEGFA signaling pathway." (PMID 35292059, 2022). "Some studies have shown that Ang2 cooperates with VEGFA to promote tumor angiogenesis and metastasis." (PMID 35805939, 2022). "VEGFA is overexpressed in tumor cells, and VEGFA protein secreted by tumor cells and surrounding stroma induces the formation of new blood vessels, leading to tumor outgrowth, metastasis, and prognosis." (PMID 35054929, 2022). "NPC-derived mast cells have a high anti-tumor TNF to angiogenic VEGFA ratio, implying high anti-tumor capacity, whereas mast cells in other malignancies are generally pro-tumorigenic." (PMID 35311066, 2022). "Tumor angiogenesis plays a key role in the progression of gliomas, and VEGFA is a key regulator of angiogenesis." (PMID 35785190, 2022). "In the miRNA-mRNA network, decreased hsa-miR-30a prompted a high incidence of portal vein tumor thrombus (PVTT) in HCC, hsa-miR-199a-5p targeted and downregulated VEGFA to inhibit tumor angiogenesis." (PMID 35197055, 2022). "Solid tumor progression and metastasis are accompanied by angiogenesis stimulation, with VEGFA as the main factor driving tumor vascular bed expansion." (PMID 36618348, 2022). "VEGFA plays a key role in promoting tumour angiogenesis and is targeted in many anti-angiogenic therapies." (PMID 34982945, 2022). "This study investigated expression level, gene regulatory network, prognostic value, and target prediction of the CXC chemokine-VEGFA network for COAD from a tumor angiogenesis perspective." (PMID 36246978, 2022). "VM is necessary for rapid tumor proliferation, and EphA2 and VEGFA are important molecules in this process." (PMID 35595748, 2022). "HCC tumors with active TGF-β signatures display abundant expression of oncogenes (e.g., KRAS, MDM2, MTOR, IGF2, and VEGFA), strengthening the model that a functional link exists between tumor promoting TGF-β and oncogenic circuits." (PMID 35205692, 2022). "HCC tumor growth relies heavily on the neoangiogenesis pathway involving growth factors such as vascular endothelial growth factor A (VEGFA) and platelet-derived growth factor (PDGF)." (PMID 36139683, 2022). "At present, a large number of studies have confirmed that VEGFA plays a vital role in tumor growth, metastasis and angiogenesis." (PMID 35668376, 2022). "The reason for this is not clear, although it seems that some aspects of the angiogenic environment stimulated by VEGFA-stimulated angiogenic milieu (high levels of microvascular permeability and density) are capable of promoting tumor expansion." (PMID 35069936, 2022). "Meanwhile, tumor volumes in mice increased as well as tumor neovascularization and VEGFA and CD31 amounts." (PMID 35832644, 2022). "The knockdown of linc00958 inhibited RSF-1 and Ki67, curbing tumor growth; it also inhibited VEGFA and CD34, decreasing angiogenesis in mice." (PMID 36056431, 2022). "Neutrophils play an important role in promoting tumour angiogenesis by producing pro-angiogenic factors such as VEGFA." (PMID 35464051, 2022). "VEGFA secreted by tumor cells and the surrounding stroma induces endothelial cell proliferation, enhancing angiogenesis." (PMID 35832644, 2022).
tumor (continued). "VEGFA and TNF are key determinants of mast cell activity with pro-tumorigenic or suppressive roles respectively and the VEGFA:TNF ratio acts as a surrogate marker of tumor progression." (PMID 36253784, 2022). "In conclusion, swimming significantly attenuates tumor growth in CT-26 tumor-bearing mice by inhibiting tumor angiogenesis via the suppression of the HIF-1α/VEGFA pathway." (PMID 35291563, 2022). "VEGFA, secreted by tumor and stromal cells, has indeed been shown to impact on cancer biology in various ways, through both autocrine and paracrine mechanisms." (PMID 35710947, 2022). "Our study demonstrated that Lis monotherapy tended to inhibit tumor growth and VEGFA expression, but compared with the control group, the difference was not statistically significant." (PMID 35847929, 2022). "Given this situation, the prominent role of VEGFA for tumor vasculature has been recognized as a feasible target for anticancer treatment." (PMID 35203290, 2022). "The mRNA expression of VEGFA was significantly downregulated in tumor tissues of the swimming group (P < 0.05; vs control group), while the mRNA of VEGFR2 remained unchanged in tumor tissues between the control and swimming groups (P > 0.05)." (PMID 35291563, 2022). "Studies have shown that Ang2 can also enhance tumor angiogenesis, promoting the expression of several growth factors, including VEGFA." (PMID 35805939, 2022). "In fact, treatment of GPx2 KD tumor-bearing mice with echinomycin, a drug that inhibits HIF1α, reduced VEGFA expression and tumor growth, while improving vessel maturation, underscoring the effect of GPx2 loss on vascular malfunction." (PMID 35193955, 2022). "Elevated levels of HIF1A, its target CAIX, and VEGFA transcripts are also seen in tumours with a gain of function or amplification of YB-1, although this was not the case for G3BP1 or NFE2L2 (encoding NRF2)." (PMID 34294889, 2022). "VEGF/VEGFR pathway is the major signaling that promotes tumor angiogenesis, especially VEGFA and its ligand VEGFR2, which have definite and critical function in tumor angiogenesis and have been utilized as therapeutic targets for cancer treatment." (PMID 36130933, 2022). "Reduced Cx43 expression increases VEGFA expression in mouse tumor cells, thereby promoting tumor angiogenesis." (PMID 35783340, 2022). "Genetic deletion of POSTN in RIP1-Tag2 mice blunted tumor rebounds of M2-like macrophages and αSMA+ stromal cells in response to prolonged VEGFA inhibition." (PMID 36077762, 2022). "More attention was focused on the VEGFA due to its key roles in tumor growth and metastasis and eye disease." (PMID 35054929, 2022). "In breast cancer, lncRNA MALAT1 sequesters miR-140 in order to upregulate VEGFA expression to promote tumor angiogenesis." (PMID 36010595, 2022). "CXCL10 promotes the proliferation of GAMS, and the elevated level of VEGFA promotes tumor angiogenesis." (PMID 36159780, 2022). "The application of trap antibodies opens the promise of localized targeting of the TGF-β and VEGFA pathways within the tumor microenvironment." (PMID 35577211, 2022). "Mechanistic studies identified 715 upregulated and 629 downregulated transcripts (including VEGFA) in tumor tissues derived from CT-26 cells in vivo after swimming." (PMID 35291563, 2022). "Vascular endothelial growth factor A (VEGFA) is a vital factor that plays an essential role in tumor angiogenesis and development." (PMID 36246978, 2022). "Several genes involved in tumor proliferation, migration, and angiogenesis, including vascular endothelial growth factor A (VEGF-A), are transcriptionally increased in tumor cells." (PMID 35869130, 2022). "Vascular endothelial growth factor-A (VEGF-A) induces angiogenesis, which is required for tumor growth." (PMID 35335890, 2022). "Since VEGFA is a major player in tumor endothelial biology, a brief summary of VEGFA-dependent EC events will be provided." (PMID 35216427, 2022).
tumor (continued). "Tumor lysates were subjected to ELISA, which revealed significantly decreased expression of VEGFA, EPO, SDF-1α, and SCF protein in tumor lysates from mice treated with 32-134D (P < 0.05)." (PMID 35499076, 2022). "Previous reports have shown that PELP1 regulate the phosphorylation of STAT3 (p-STAT3), and STAT3 regulate the expression of VEGFA to affect the angiogenesis of tumor." (PMID 35053547, 2022). "VEGFA is widely expressed by tumor cells and acts through VEGF receptors to induce angiogenesis, by increasing microvascular permeability, promoting endothelial cell survival, division and migration, and prevent senescence, etc.." (PMID 35695994, 2022). "Tumor vasculature is known to be highly abnormal due to unbalanced, local overexpression of a small number of growth factors, particularly vascular endothelial growth factor-A (VEGF-A)." (PMID 35203573, 2022). "VEGFA is a factor of endothelial cells during tumor angiogenesis and functions in antiapoptosis and vasodilation." (PMID 36430344, 2022). "For example, some tumor cells express receptors for VEGFA, such as VEGF-R2 and neuropilins, and VEGFA signaling in these cells is associated with aggressive behavior, including the acquisition of stem-like traits." (PMID 35710947, 2022). "Our scRNA-seq data confirmed a fivefold reduction in GPx2 mRNA in the GPx2 KD tumor and violin plots confirmed a dramatic increase in HIF1α and VEGFA mRNAs in most of the clusters that make up the GPx2 KD tumor." (PMID 35193955, 2022). "The high expression of TGF-β, VEGFA, and CXCL10 and the low expression of TNF-α indicated the tumor-supporting effect of GAMs in high risk score group." (PMID 36159780, 2022). "It has been reported that VEGFA is mainly secreted by tumor cells, endothelial cells, and infiltrating myeloid cells in the tumor microenvironment, indicating hypoxia in the local microenvironment." (PMID 36741702, 2022). "CXCL5 belongs to the CXC-type chemokine family, and studies showed that CXCL5 regulated the expression of FOXD1 and VEGFA and promoted tumor angiogenesis by activating the AKT/NF-κB pathway." (PMID 36286020, 2022). "Studies have verified that the PI3K/AKT signaling pathway participates in tumor angiogenesis by regulating several pro-angiogenic cytokines, such as VEGFA and MMP9." (PMID 35436935, 2022). "In fact, CAFs directly enhance tumor angiogenesis through producing pro-angiogenic factors like vascular endothelial growth factor A (VEGFA), fibroblast growth factor 2 (FGF2), CXCL12, and PDGFC." (PMID 36465388, 2022). "Many tumor cells secrete the glycoprotein vascular endothelial growth factor-A (VEGF-A), which binds to VEGFR-1 and VEGFR-2." (PMID 36430176, 2022). "The expression of VEGFA is involved in tumor proliferation and motility in PDAC, and a higher abundance is associated with a worse prognosis." (PMID 36139787, 2022). "ICAM-1 expressed on LSECs promotes the secretion of IL-6, prostaglandin E2, VEGF and MMP2 by tumor cells, which in turn induces HSCs to secrete VEGFA and MMP2." (PMID 35965533, 2022). "As expected, the cytoplasmatic VEGFA/165b expression is higher in invasive tumor cells than in normal tissues or stroma." (PMID 35303290, 2022). "Given the critical role of VEGFA in tumor angiogenesis and a perfect anticancer target, the translational regulation of VEGFA has received growing attention." (PMID 35054929, 2022). "During tumour vessel normalisation, the pro- and anti-angiogenic factors, such as VEGFA and ANG2, come to a balance—pericyte coverage and perfusion increase and hypoxia decreases." (PMID 36077754, 2022). "In a xenograft mouse model of MM, binding of clodronate liposomes (Clo) to VEGFA siRNA significantly suppresses tumor growth." (PMID 35958625, 2022). "Tumor angiogenesis controlled predominantly by vascular endothelial growth factor and its receptor (VEGF-VEGFR) interaction plays a key role in the growth and propagation of cancer cells." (PMID 34928481, 2022).
tumor (continued). "VEGFA plays a crucial role in the control of angiogenesis, including tumor development and progression." (PMID 35966715, 2022). "The levels of ligand and receptor genes indicate that macrophages with high levels of VEGFA play an important role in tumor tissues." (PMID 36531216, 2022). "VEGFA has also been reported to upregulate the expression of Fas ligand (FasL/CD95L) of the tumor vasculature, which specifically induces apoptosis of CTLs but not Tregs." (PMID 35577211, 2022). "Specifically, stromal fibrosis and the induction of VEGFA from tumor cells promote tumor regrowth and angiogenesis." (PMID 36612017, 2022). "The regulatory effects of anti-angiogenic drugs targeting VEGFA/VEGFR2 in immune cells, including CD8+T cells, Tregs, MDSCs, DCs, tumor-associated macrophages and mast cells were worth of further study." (PMID 36260222, 2022). "VEGFA is one of the major cytokines released from tumor cells to induce endothelial cells angiogenesis." (PMID 36467048, 2022). "Vascular endothelial growth factor A (VEGFA) is a well-known factor that plays critical roles in angiogenesis, and it is mainly released by tumor cells during the development of tumors." (PMID 36376862, 2022). "A second methylation target site of SETD7 on HIF-1α protein (K391) also destabilises HIF-1α but can be reversed by the lysine-specific histone demethylase 1A (also known as LSD1) to induce VEGFA transcription and tumour angiogenesis." (PMID 35326563, 2022). "A promising candidate for molecular targeting strategies focusing on the TME is vascular endothelial growth factor-A (VEGF) and its receptor VEGFR2 for use on tumor-associated endothelial cells that together have a key role in tumor neovascularization." (PMID 35565307, 2022). "Hypoxia further promotes angiogenesis, epithelial-mesenchymal transition, and tumor metastasis through vascular endothelial growth factor A (VEGFA) or HIF-1, exacerbating hypoxia and immunosuppression, and patients are less likely to benefit from this therapy." (PMID 35844616, 2022). "A posterior work demonstrated that HMGA1 interacts with the TF FOXM1 to promote tumour angiogenesis in TNBC through the transcriptional activation of vascular endothelial growth factor A (VEGFA)." (PMID 35267409, 2022). "Stickingly, VEGFA-blocking antibodies significantly delayed tumour progression in a melanoma model (B16 cells) when combined with a CAR T engineered to recognize a tumour specific antigen." (PMID 36505819, 2022). "In our preliminary study in HCC and non-tumor tissue samples (n = 40), we observed higher expression of VEGFA in tumor tissues than in non-tumor samples." (PMID 35205327, 2022). "Our study suggests that lncRNA RP11-732M18.3 promotes tumor angiogenesis in mouse models and increases the level of VEGFA both in glioma cells and cell-free supernatants." (PMID 35785190, 2022). "The results indicated that in the primary tumor, endothelial cells exhibited strong connections with mast cells, fibroblasts, and epithelial cells by the VEGFA signaling pathway and TGF-β signaling pathway." (PMID 36569924, 2022). "Intravital high-resolution microscopy revealed that perivascular macrophages promote transient vascular permeability by interacting with endothelial cells, via VEGFA signaling, and consequently facilitate the intravasation of tumor cells." (PMID 35207611, 2022). "Tumor angiogenesis mainly relies on the response driven by vascular endothelial growth factor A (VEGFA)." (PMID 35433661, 2022). "ITGB3 has been reported to play an important role in promoting tumor angiogenesis through enhancing transcriptional activation of VEGFA by β-catenin." (PMID 36130933, 2022). "While many HDAC4 targets have been identified, they focused on HIF-1α, one of the central players of tumor progression and drug response and VEGFA, one of the best-characterized HIF-1α targets." (PMID 36014432, 2022).